EPHB4 (EPH receptor B4)
Diseases named in the same sentence as EPHB4 in open-access papers (continued):
Sharing a sentence is not in itself a finding about the gene and the disease.
tumor (continued). "In this tumor, EphB4 signaling can be induced by its ligand EphrinB2 or by the cross-talk with PDGFRβ, which facilitates PDGF ligand-dependent, ephrin ligand-independent activation of EphB4." (PMID 34440844, 2021). "To determine whether EPHB4 is a suitable target for EPHB4-CAR-T cells, we investigated the expression of EPHB4 in tumor cells." (PMID 33816783, 2021). "Complicating matters further, it has been reported that EphB4 can exert tumour-suppressor effects independent of ligand stimulation, e.g., through a decrease in integrin-mediated adhesion." (PMID 33430066, 2021). "In addition, the aberrant activation of NOTCH1 in CRC, specifically serrated neoplasia pathway, leads to an increase in Ephrin type-B receptor 4 (EPHB4), which promotes tumor growth and cell migration." (PMID 33478063, 2021). "EphB4 is known to be expressed in the vasculature in mouse embryos but not in adult animals except for the tumor vasculature." (PMID 34298619, 2021). "The mean score of EphB4 staining did not vary significantly between different tumor stages in the test cohort and validation cohort." (PMID 32751634, 2020). "While, majority of tumor tissues showed a high expression of EphB4, normal urothelial cells displayed very little or lack of EphB4 expression." (PMID 32795296, 2020). "This means that neither NVP nor NVPiso were able to significantly prevent the EphB4-induced effects on tumor growth, vascularization, perfusion, and hypoxia." (PMID 33153234, 2020). "The NVP treatment completely reversed the upregulation of p-EphB4 in xenograft tumors of the PDCD10-knockdown mice Consequently, the tumor progression was significantly faster in the shPDCD10-mice than that in the controls as inspected from day 7 to day 21 after implantation." (PMID 32850441, 2020). "Overexpression of EphB4 seems to be applicable for imaging purposes irrespective of the stage of the tumor." (PMID 32751634, 2020). "Next generation sequencing revealed that transcription levels of EphB4 in GBM were drastically increased than those in non-tumor (data not shown; log2FC = 2.33; P < 0.0001)." (PMID 32850441, 2020). "In EphB4 overexpression groups, tumor volume was not affected by sunitinib treatment displaying similar growth behavior between placebo- and sunitinib-treated groups both in the subcutaneous and orthotopic model." (PMID 29987450, 2018). "In a previous study that predominantly was performed for radiopharmacological characterization of a novel EphB4 targeting radioligand in 12 mice no substantial difference in tumor growth between EphB4 and mock transfected A375 tumors was observed." (PMID 29462967, 2018). "We demonstrated EphB4 to be a positive regulator of tumor growth, but a negative regulator of tumor vascularization and perfusion, resulting in increased tumor hypoxia." (PMID 29462967, 2018). "Influence of EphB4 on tumor angiogenesis is not surprising since EphB4 receptor and its preferred ligand EphrinB2 are essential regulators of embryonic blood and lymph vascular morphogenesis." (PMID 29462967, 2018). "In particular, by in vivo PET imaging it became evident that EphB4 overexpression increased hypoxia especially in ‘smaller’ tumors (sum of A375-pIRES and A375-EphB4 tumor volumes < 1582.3 mm3) which were normally not yet hypoxic." (PMID 29462967, 2018). "Experimentally, inhibition of EphB4 with VasG3 in both aRMS and eRMS orthotopic xenograft and allograft models failed to alter tumor progression." (PMID 28817624, 2017). "EphB4 signaling can be induced by trans interactions with its cognate ligand, EphrinB2, typically expressed in the tumor microenvironment on endothelial; or by cis interactions with PDGFRβ expressed on RMS tumor cells." (PMID 28817624, 2017).
tumor (continued). "Inhibition of EphB4 forward signaling using soluble EphB4 protein fused with murine serum albumin failed to affect eRMS model tumor progression, but did moderately slow progression in murine aRMS." (PMID 28817624, 2017). "Neither EphB4/EphrinB2 inhibition with soluble EphB4 nor VasG3 treatment demonstrated an effect on survival or tumor growth rates in human eRMS PDX models." (PMID 28817624, 2017). "A paired tumor model containing EphB4-positive (SKOV3) and EphB4-negative (A549) tumors were further employed to investigate the EphB4-mediated tumor delivery of HP-TCS." (PMID 28942682, 2017). "As a target for tumor imaging, a low grade of expression of both EphA2 and EphB4 in normal tissue is essential and has not been thoroughly investigated." (PMID 28165374, 2017). "Inhibition of EphB4/EphrinB2 forward signaling failed to affect eRMS tumor progression in either xenograft model." (PMID 28817624, 2017). "VasG3 inhibition of EphB4 failed to decrease eRMS tumor growth when compared to the IgG control group (p = 0.351)." (PMID 28817624, 2017). "Treatment with the humanized EphB4 inhibitory antibody failed to affect tumor growth or survival rates in both the PCB380 and Rh30 xenograft models when compared to the IgG control group." (PMID 28817624, 2017). "We next screened by flow cytometry this panel of cell tumour phenotypes with epithelial markers (EpCAM, E-cadherin, Muc1, claudin-3 andclaudin-4) or non-epithelial markers (N-cadherin, vimentin, CD66, EGFR, FGFR, EphB4,ALDH1 and CD49f)." (PMID 27711186, 2016). "Likewise, A-type receptor expression is restricted to tumor cells and B-type receptor expression is considerably higher in, or selective for, tumor cells, the latter exemplified by EPHB3 and EPHB4." (PMID 27215396, 2016). "Single tracers for EphB4 and MET have also been reported for tumor imaging." (PMID 26690113, 2015). "This study further supports the tumor promoting role of EphB4 in TCC and highly restricted expression in tumor and not normal organ, providing opportunity for targeted therapy." (PMID 25148033, 2014). "On the opposite, EphB4, FGFR1, Tie2, Alk5, TNFR2, and the adhesion molecules VCAM-1 and ICAM-1 were more frequently detected and at higher levels in normal kidney endothelium as compared to tumor endothelium from intermediate and large tumors." (PMID 22235379, 2011). "Although these studies have been conducted in a tumor cell line, the observation that EPA can change expression of EphB4 may have wider implications and should be investigated further in a wider range of biological systems." (PMID 20624275, 2010). "Seven of 10 tumour specimens expressed EphB4 on Western blotting (data not shown), confirming the staining data." (PMID 17353927, 2007). "While the single transgenic EphB4 animals did not develop tumours during this experiment it is possible that these studies were not taken out far enough to conclude that EphB4 over-expression is insufficient to induce transformation with a long latency." (PMID 16171530, 2005). "Our findings reveal that EphB4 knockdown in cancer cells leads to an increase in the development of distant metastases, characterized by a pro-metastatic cancer cell phenotype, systemic immunosuppression, and enhanced infiltration of CD4+ T cells and Tregs into the tumor." (PMID 39091728, 2024). "Although some studies show that EphB4 does not lead to significant changes in the tumor vasculature, EphB4 may regulate vascularization and angiogenesis." (PMID 38651144, 2024). "EPO, acting through the canonical EPO-R or through ephrin-type B receptor 4 (EphB4), an alternative EPO-R, may account for the increased tumor growth and progression through downstream activation of the Src-STAT3 pathway seen in cancer patients treated with ESAs." (PMID 37543610, 2023).
tumor (continued). "In particular, EphA2, EphA3, EphA4, and EphB4 are promising therapeutic candidates, based on increased expression in tumours and the TME, and drugs targeting these receptors have shown some promise in tumour models, with mixed success in the limited clinical studies performed to date." (PMID 36830852, 2023). "However, stimulation of EphB4 alone, in the absence of pro-tumor ligand signaling, fails to impart any anti-tumoral benefit." (PMID 35725568, 2022). "Moreover, transient expansion of human PBMC‐derived CAR‐T cells was achieved in the CAR‐T group, and no acute on‐target/off‐tumor toxicity was observed when EPHB4 molecules were targeted by their natural ligand, Ephrin B2." (PMID 34123382, 2021). "However, the exact molecular mechanisms downstream of EphB4 activation leading to tumor cell proliferation and metastasis are not known, and further studies are required to investigate the underlying pathways and protein-protein interactions." (PMID 34298619, 2021). "Therefore, EPHB4 may be a potential indicator of tumour metastasis and poor prognosis in OSCC patients, which indicates the great significance of studying the role of EPHB4 in OSCC." (PMID 34539874, 2021). "All of the four circulating mRNAs, including CK7, ELF3, EGFR, and EphB4 mRNA, were strongly associated with NSCLC patients’ prognosis; however, the association of the cell-free RNA content with patient survival was independent of the tumor stage." (PMID 27827952, 2016). "Finally, in addition to improved anti-tumor efficacy, simultaneous blockade of Dll4/Notch and Ephrin-B2/EphB4 abolished the liver vascular lesions seen when only Dll4/Notch is inhibited." (PMID 21092311, 2010). "Importantly, although EphB4-induced neoangiogenesis does not appear to be important for tumor progression, its expression may confer important migratory capabilities to CRC cells." (PMID 38651144, 2024). "Given the parallel increase in EphA4 protein levels and its phosphorylation status, we questioned whether hyperactivation of EphA4 plays a dominant role in stimulating tumor growth in the absence of cancer cell EphB4 and whether we can reverse it by using the pharmacological intervention." (PMID 35725568, 2022). "Interestingly, the application of NVP-BHG 712 under endothelial Ephrin-B2 depletion did not result in antimetastatic effects, which might be explained by the missing activation of tumor cell-bound EphB4 in the absence of endothelial Ephrin-B2." (PMID 34360793, 2021). "Moreover, blocking of EphB4 forward signaling did not alter A375-EphB4 tumor growth." (PMID 29462967, 2018). "The identified endothelial signalling pathway of CCM3‐DLL4/Notch‐EphB4‐Erk1/2 may provide an insight into mechanism of CCM3‐ablation‐mediated angiogenesis and could potentially contribute to novel therapeutic concepts for disrupting aberrant angiogenesis in CCM and in hyper‐vascularized tumours." (PMID 28371279, 2017). "We had previously demonstrated that EphB4 is predominantly expressed in cancer cells in various HPV-negative models of HNSCC and that its knockdown or knockout accelerates local tumor growth in the absence of radiation therapy (RT)." (PMID 39091728, 2024). "Although a previous study demonstrated that siPF inhibited growth and induced differentiation of Rh30 cells, we did not observe additional anti-tumor efficacy in siPF-RMS cells, which were co-cultured with EPHB4-CAR-T cells." (PMID 33816783, 2021). "The PB-EPHB4-CAR-T cells inhibited EPHB4-positive tumor cells without activating cell proliferation downstream of EPHB4, even after multiple tumor re-challenges and suppressed tumor growth in xenograft-bearing mice." (PMID 33816783, 2021). "Patient tumor specimens (non-responders=13; responders=9) obtained from a clinical trial NCT01218048 were subjected to multispectral VECTRA staining for epithelial cell marker cytokeratin 7 (CK7), EphB4, and ephrinB2." (PMID 35725568, 2022).
tumor (continued). "In addition, robust expression of the EphB4/EphrinB2 blocking TNYL‐RAW peptide did not reduce vascular p‐EphrinB in B16F10 tumor‐bearing mice." (PMID 34102002, 2021). "Second, although EPHRIN B2-dependent interactions with EPHB4 are associated with cellular proliferation, and the blockade of EPHRIN B2-EPHB4 binding may be a therapeutic target in some tumor cells, EPHRIN B2-dependent interactions with EPHB4 do not promote cellular proliferation in RMS cells." (PMID 33816783, 2021).
cancer (86 papers, 2005 to 2026). A tumor composed of atypical neoplastic, often pleomorphic cells that invade other tissues. "The EphB4-ephrinB2 signaling axis has been heavily implicated in metastasis across numerous cancer types." (PMID 39091728, 2024). "Loss of EphB4 in cancer cells induces protein dysregulation concomitant with increased metastatic capacity." (PMID 39091728, 2024). "The recent identification and cloning of a third isoform variant in cancer (DTX3c), and its specific involvement in EphB4 degradation in cancer cells, sheds further light on this group of proteins and their specific role in cancer." (PMID 37443713, 2023). "Our initial observation associating cancer IGF-II secretion with EphB4-expression in solid malignancies led us to a search for a cause-effect link between the two co-expressed oncogenic cellular events." (PMID 37823054, 2023). "As EphB4 is a key binding partner to ephrinB2 and given its high levels of expression on the cancer cells, we next investigated the effect of EphB4 loss-of-function in different orthotopic syngeneic models of HNSCC." (PMID 35725568, 2022). "Loss of EphB4 on the cancer cells elicits a robust compensatory effect mediated by EphA4 and results in an influx of immunosuppressive regulatory T cells (Tregs)." (PMID 35725568, 2022). "EphA2 and EphB4 are upregulated in many types of cancers and are associated with increases in cancer malignancy and poor prognosis." (PMID 31333644, 2019). "The EphB4 gene encodes for a transmembrane tyrosine kinase receptor involved in embryonic blood vessel differentiation and cancer development." (PMID 31810288, 2019). "The degree to which these NS EPHB4 mutations occur exclusively from aberrations in common cancer-associated genes is remarkable." (PMID 26073592, 2015). "To investigate whether EphB4 loss enhances cancer cell migration, we employed Transwell Boyden chamber assays." (PMID 39489818, 2025). "Interestingly, EphB4 knockdown in cancer cells was associated with an increase in the incidence of lung (MOC2) or mediastinal lymph node (LY2) metastases." (PMID 39489818, 2025). "To investigate whether EphB4 inhibition enhances metastasis through a canonical cancer-cell centered mechanism, we explored intrinsic changes induced by loss of EphB4 in the cancer cell using RNA sequencing." (PMID 39091728, 2024). "Interestingly, EphB4 knockdown in cancer cells was associated with an increase in the incidence of lung (MOC2) or mediastinal (LY2) metastases." (PMID 39091728, 2024). "The DTX3c behavior in this study was clearly opposed to the cancer-promoting effects linked to IGF-II- /EphB4 overexpression described in the literature support a tumor-suppressing role for DTX3 similar to other studies reviewed herein in cancer cellular models." (PMID 37443713, 2023). "Since RNA-seq data in our preclinical model displayed transcriptomic changes following EphB4 loss on the cancer cell particularly in pathways regulating angiogenesis, cell survival, and IFN-gamma related gene signatures, we expanded our analysis to the HNSCC TCGA datasets of interest." (PMID 35725568, 2022). "EphB4 has been found overexpressed in malignant cancer cells where it has been associated to a variety of cancer-promoting effects, including morphogenesis, angiogenesis, invasion, and metastasis and its pharmacologic block or kinase activity deficiency counteracts such effects." (PMID 31270394, 2019). "All together, these observations provide the rational for foreseeable studies aimed at the identification of the molecular components responsible for the observed regulation of the EphB4 phosphodegron by the IGFII/IRA stimuli towards causing EphB4 over-expression in cancer." (PMID 31270394, 2019). "Additionally, EphB4 knockout cells had increased expression of matrix metallopeptidase 14, pinin, and keratins 7, 8, 16, and 20, genes associated with increased proliferation, and metastasis across multiple cancer types." (PMID 39489818, 2025).